INS (insulin)
Diseases named in the same sentence as INS in open-access papers (continued):
Sharing a sentence is not in itself a finding about the gene and the disease.
diabetes (continued). "The majority of people with diabetes requiring basal-bolus therapy depend on an insulin pen or syringe to deliver multiple injections of insulin per day, which can be burdensome." (PMID 31833010, 2020). "Among adults, out-of-pocket spending for diabetes-related supplies ($445) and insulin ($427) were similar." (PMID 32478819, 2020). "PAX4-MODY is characterized by ketosis-prone diabetes mellitus which is managed with diet, OADs, or insulin." (PMID 33292863, 2020). "Diabetes-related factors of glycemic control, medication pharmacodynamics, and insulin access can impact the severity of a COVID-19 infection." (PMID 32392473, 2020). "Type 1 diabetes mellitus (T1DM) is typically caused by an autoimmune response leading to the destruction of β-cells in the pancreas, and an absolute deficiency in insulin." (PMID 33126498, 2020). "More than two-thirds (69.8%, n = 15,847) reported taking medication to manage their diabetes, the most common were Metformin (54.9%, n = 12,475), Insulin (19.1%, n = 4,336), and the sulphonylureas (20.8%, n = 4,723)." (PMID 32754618, 2020). "This can also be due to diabetes-related comorbidities (e.g., hypertension, dyslipidaemia), or can be an effect of hyperinsulinemia or impaired insulin response." (PMID 32503113, 2020). "Investigations have studied the efficacy of mealtime WP in patients that do not represent the wider T2D population, excluding those with more advanced diabetes and treated with insulin regimens." (PMID 33195375, 2020). "Failure of the insulin function system, referred to as insulin resistance, is an element of prime importance that characterizes diabetes mellitus." (PMID 33270683, 2020). "As in other developing countries, the Saharawi refugee camps also have a poor supply of glucose-lowering drugs and insulin, as well as materials, reagents, and tools for diabetes diagnosis and monitoring." (PMID 32098332, 2020). "This target was chosen, considering that this enzyme acts as a negative regulator of insulin and leptin dependent signal cascades holding therapeutic utility in type 2 diabetes mellitus and obesity." (PMID 32752292, 2020). "PA reduces insulin sensitivity in hepatocytes and skeletal muscle, and thereby contributes to the development of type 2 diabetes mellitus (T2DM)." (PMID 32542540, 2020). "Corn starch was added for all patients at diagnosis to prevent morning hypoglycemia while small doses of NPH insulin were given to treat diabetes." (PMID 33292488, 2020). "The present study also shows that ucOC correlates with IGI independent of BMI, thereby indicating it to be a novel factor to correlate with insulin secretion in individuals with diabetes." (PMID 32821293, 2020). "It should also be emphasized that our diabetes group had been on intensive insulin treatment for at least ten years." (PMID 32309448, 2020). "We found several plasma metabolites that are associated with early disturbances in glucose metabolism and insulin sensitivity of which five were also higher in individuals with diabetes mellitus." (PMID 32124065, 2020). "Common variables for diabetes were also identified by machine learning methods, such as genetic factors, hypertension, insulin, and so on." (PMID 32157171, 2020). "It was difficult to obtain accurate serological indicators of diabetes, such as serum insulin and C-peptide levels, especially in some individuals with prediabetes." (PMID 33318573, 2020). "In patients suffering pre-diabetes or diabetes, insulin resistance affects glucose uptake in response to insulin mainly in their skeletal muscle, liver and adipose tissue, leading to development of high glycemia." (PMID 32708537, 2020). "Both insulin and glucagon have been of significant focus, due to the key roles in glucose metabolism, diabetes and other disorders." (PMID 32296396, 2020).
diabetes (continued). "All, but 24 recipients were already on other pharmacotherapy for diabetes, with the insulin being the most commonly used agent, either alone (6 patients, 35%), in combination with metformin (5 patients, 29%), or glipizide and pioglitazone (1 patient, 6%)." (PMID 32095510, 2020). "In sum, our study suggests that high levels of T3 can induce ERS and result in insulin resistance and insulin secretion in β-cells, thereby contributing to the pathogenesis of diabetes." (PMID 32774144, 2020). "Diabetes mellitus is a metabolic disorder characterized by the impaired response to insulin and decreased insulin secretion in the body, resulting in chronic hyperglycemia." (PMID 33817224, 2020). "Diabetes, as a metabolic disease, is indicated by hyperglycemia resulting from defects in insulin secretion, insulin action, or both." (PMID 32842548, 2020). "The immense impact of PPARα on glucose homeostasis and insulin signaling is particularly well illustrated by pancreas malfunction and diabetes models." (PMID 32708786, 2020). "The expression of MafA gene is down-regulated, thus inhibiting the transcription of insulin in diabetes mellitus." (PMID 32038500, 2020). "Diabetes is a debilitating metabolic disease characterized by high blood glucose resulting from defects in insulin production, insulin signaling, or both." (PMID 32371554, 2020). "The Diabetes Control and Complications Trial showed that intensive insulin replacement therapy reduces the incidence and slows the progression of DR." (PMID 32977483, 2020). "Retardation of insulin action, such as in diabetes mellitus, activates gluconeogenesis during the fed state." (PMID 33005004, 2020). "Diabetes is a metabolic disorder resulting from impaired insulin secretion and/or insulin resistance that modulates carbohydrate metabolism." (PMID 33330130, 2020). "Liver total CoA levels and hepatic PanK activity are altered in response to nutritional state, insulin, glucagon, glucocorticoids, fibrate, and diabetes." (PMID 33260564, 2020). "A 47-year-old man with diabetes said: “When you work for 10 to 14 hours a day, it is hard to keep a diet and inject insulin twice a day." (PMID 33072199, 2020). "Diabetes is characterized by chronically increased peripheral insulin levels and concomitantly reduced brain insulin activity." (PMID 32655364, 2020). "The autoimmune disease T1DM (type 1 diabetes mellitus) is characterized by the selective destruction of insulin-producing pancreatic beta-cells by autoreactive T cells, absolute insulin deficiency and subsequent hyperglycemia." (PMID 32226409, 2020). "All in all, the differences in corrected α-tocopherol concentration, insulin resistance, β-cell function and serum RAGE concentration in subjects of different ethnicities gives rise to different risk profiles of diabetes." (PMID 33261162, 2020). "One of the other factors associated with insulin gene therapy for T1DM is increased bodyweight, as diabetes improves, as confirmed by our meta-analysis." (PMID 32489555, 2020). "Their study showed that an array of hollow 21 μm × 400 μm long microneedles, connected to an electrically controlled drug dispenser with a 12 μL reservoir, increased the plasma insulin level and minimized risks for diabetes-induced complications." (PMID 32325974, 2020). "Type 2 diabetes mellitus (T2DM) is caused by abnormalities of controlling blood glucose and insulin homeostasis." (PMID 32471242, 2020). "Like ob/ob mice, db/db mice are insulin-resistant and develop obesity and diabetes while they are leptin-resistant in contrast to ob/ob mice." (PMID 32566684, 2020). "Clinicians manage the symptoms and progression of diabetes through several pharmacological agents that decrease hepatic gluconeogenesis, increase glucose disposal, increase insulin sensitivity, or increase insulin secretion." (PMID 32444674, 2020).
diabetes (continued). "Diabetes mellitus is a group of physiological dysfunctions characterized by hyperglycemia resulting directly from insulin resistance or inadequate insulin secretion leading to macrovascular and microvascular complications with time." (PMID 33294430, 2020). "According to the World Health Organization, diabetes occurs when the pancreas produces too little insulin for the body's requirements, or when the body cannot use insulin effectively." (PMID 33552541, 2020). "Where reported, the majority of each population was married; use of insulin during pregnancy, family history of diabetes and being overweight were common." (PMID 31317569, 2020). "The characterization of different populations of β-cells based on their UPR and insulin levels is crucial in diabetes." (PMID 33613449, 2020). "The diagnosis of diabetes was made based on typical clinical presentation and the need for insulin since diagnosis." (PMID 32313169, 2020). "PPARγ activators have been used as type 2 diabetes mellitus treatment, acting as insulin sensitizers but with important secondary effects like increased lipogenesis or lipogenic intake in the liver, leading to steatosis." (PMID 32120804, 2020). "Undoubtedly, understanding the basic mechanisms of β-cell insulin secretion by islet stellate cells (ISCs) is essential to further elucidate the regulation of β-cell function and the prevention and treatment of diabetes." (PMID 32184820, 2020). "The availability of genetically modified mouse and rat models, which spontaneously develop diabetes, allows known molecular mechanisms of pancreatic insulin-producing cells to be destroyed, especially with reference to type I diabetes." (PMID 32192078, 2020). "Mean (SD) annual out-of-pocket spending for insulin was lower ($435 [$544]) than spending for diabetes-related supplies ($490 [$785])." (PMID 32478819, 2020). "Patients with diabetes on insulin were excluded because elevated blood glucose levels preclude accurate 18F-FDG uptake measurements." (PMID 31202739, 2020). "For several decades, diabetes research has been focusing on insulin resistance and the consequent defects in pancreatic β-cells and insulin secretion." (PMID 32218947, 2020). "The extract of Forsythia suspensa exhibited a significant antihyperglycemic and antihyperlipidemic effect in the treatment for diabetes by modulating oxidative stress and insulin secretion." (PMID 32566084, 2020). "The beneficial effects of C. zeylanicum in the body consist of diabetes-associated weight loss control, HDL cholesterol booster, reduction of fasting blood glucose, and increasing circulating insulin levels." (PMID 32435657, 2020). "It has multiple therapeutic actions on diabetes mellitus and its complications, including regulation of glucose and lipid metabolism, improvement of insulin sensitivity, and alleviation of oxidative damage." (PMID 31734944, 2020). "It was also reported that Nrf2 activation by Keap1 knockout protects from obesity-induced diabetes by improving both insulin secretion and insulin resistance, thus resulting in the prevention of hyperglycemia." (PMID 33238435, 2020). "More than half of thepatients with T2DM were treated with insulin and had duration of diabetes forless than 10 years." (PMID 33996077, 2020). "With the increasing prevalence of diabetes, both worldwide and nationally, and the continuous technology advancement of the insulin pump that improves glycemic control, we believe that it will gain more popularity in the coming years." (PMID 33334003, 2020). "Such relation was observed in the diabetes mellitus subgroup analysis of the ABSORB trials and in a pooled analysis of the SPIRIT and COMPARE trials; both analyses found insulin-treatment to be a risk factor for TLF after PCI with either EE-BRS or EES." (PMID 33008407, 2020). "The use of high-concentration formulations of insulin is becoming more prevalent in the management of patients with diabetes mellitus." (PMID 32342025, 2020).
diabetes (continued). "Diabetes management has advanced recently in different aspects, particularly for patients who require insulin therapy." (PMID 33334003, 2020). "The administration of PON1, prior to streptozotocin-induced diabetes, led to decreased diabetes onset rates and higher insulin levels." (PMID 31430977, 2019). "Apart from these processes, mounting evidence suggests that specific features of diabetes, namely impaired glucose metabolism and insulin signaling, play a key role in the brain during AD." (PMID 31293498, 2019). "Understanding the molecular basis of AT response to insulin is important for the pharmacotherapy of diabetes, also in relation to the peculiar effects of specific insulin analogues on fat expansion and weight gain." (PMID 30754657, 2019). "Consistent with previous studies, we found that adherence to antihyperglycemic medications was suboptimal among patients with diabetes on insulin therapy." (PMID 31976334, 2019). "Diabetes mellitus, a global disease characterized as an impairment in insulin secretion (type 1 diabetes mellitus), insulin resistance (type 2 diabetes mellitus) leads to hyperglycemia, and are two of the most important health problems faced by every country." (PMID 30862104, 2019). "Diabetes mellitus (DM) is a chronic metabolic disorder characterized by increased blood glucose level, hyperglycemia, and glucosuria, which are usually caused by deficiency in insulin secretion and/or insulin hormone activity in the pancreatic beta cells." (PMID 31652041, 2019). "Insulin and oral anti-diabetic agents are important treatments of diabetes, but they also have various side effects (Gilbert and Pratley, 2009 ▶)." (PMID 31516857, 2019). "All forms of diabetes are characterised by defective signalling of insulin, the peptide hormone responsible for stimulating cellular glucose uptake." (PMID 31888259, 2019). "The effects of insulin gene dosage probably played a role in the onset of diabetes our Seriola dumerili Ins2 transgenic animals." (PMID 30899071, 2019). "Diabetes mellitus, an incurable metabolic disease, is characterized by changes in the homeostasis of blood sugar levels, being the subcutaneous injection of insulin the first line treatment." (PMID 31756981, 2019). "When transplanted into diabetic mice, the converted human α cells ameliorated diabetes and produced insulin for several months." (PMID 31686269, 2019). "In this study, in addition to a higher rate of diabetes, we found that insulin was used to treat diabetes only in East Asian cases, whereas oral anti-diabetic drugs were used in the two Caucasian cases with diabetes." (PMID 31286966, 2019). "Later on, the combination of further beta-cell dysfunction precipitates the development of diabetes due to the failure of the beta cells to compensate for more insulin release during insulin resistance." (PMID 31881657, 2019). "In this study, after 26 weeks of diabetes an increase in glycated haemoglobin, insulin and C-peptide was also present." (PMID 31798462, 2019). "Type 2 diabetes mellitus (T2DM), accounting for ~90% of individuals with diabetes, is associated with high blood glucose, insulin resistance and increased insulin secretion." (PMID 30901372, 2019). "Instead, there is likely molecular reorganization of the insulin transport system at the BBB due to diabetes." (PMID 31213970, 2019). "We selected miR-146a, miR-155, miR-320, miR-370, and miR-486 involved both in insulin sensitivity and in chronic inflammation and regulated in serum of CF patients at onset of CF related diabetes." (PMID 31920988, 2019). "Type 2 diabetes mellitus (T2DM), which accounts for 90–95% of all diabetes cases, is characterized by insulin resistance and/or impaired insulin secretion, resulting in hyperglycemia." (PMID 30641913, 2019). "Diabetes diagnosis was defined as fasting glucose ≥126 mg/dL, or self-reported hypoglycemic medication or insulin treatment." (PMID 31632346, 2019).
diabetes (continued). "Different presentations of insulin, such as insulin-based sprays, creams, and dressings, showed great success in treating the chronic ulcers of patients with diabetes mellitus, as well as in animal studies." (PMID 31652990, 2019). "Conversely, inhibition of PKD exacerbates SINGD, mitigates insulin secretion and accelerates diabetes." (PMID 31346174, 2019). "Part of the mechanism of XSN on treating PHHD syndrome by sharing pathways with insulin secretion or glucose and lipid metabolism also suggest the potential therapeutic effect of diabetes and diabetic cardiopathy." (PMID 31607935, 2019). "Type 1 diabetes mellitus is an auto-immune disease characterized by failure in insulin production as a result of pancreatic insulin-secreting islet β cells destruction." (PMID 31762718, 2019). "One in every five households (19.9%) consumes blood pressure tablets, and one in every ten households (10.5%) consumes insulin or other medicines for diabetes." (PMID 30646905, 2019). "The dynamics of insulin secretion in relation to physiological stimuli, and to diabetes complications, is less-well studied in people with long-duration type 1 diabetes." (PMID 30767048, 2019). "Adherence to renin angiotensin system antagonists (RASA), non-insulin diabetes medications (NIDM) and statins has been included in the Medicare Star Ratings program since 2012." (PMID 31269735, 2019). "Following initiation of insulin treatment with V-Go, significant improvements were observed in glycemic control, as well as reductions in insulin requirements and lower diabetes-related treatment costs." (PMID 32685581, 2019). "In conclusion, these results indicate that eight weeks of swimming training potentiates the recovery of femoral neck strength in young rats with severe STZ-induced diabetes under insulin therapy." (PMID 31038563, 2019). "In patients with diabetes, plasma insulin and glucose level imbalance result in a reduction of triglyceride-derived fatty acid membrane transport; this reduction results in increases in the half-life of triglyceride-rich lipoproteins and remnant particles." (PMID 31057650, 2019). "Antagonising glucagon signalling in patients with type 1 and type 2 diabetes also improves glycaemic control and reduces daily insulin requirements, suggesting enhanced insulin sensitivity and signalling." (PMID 30626440, 2019). "With respect to diabetes, such mechanisms include, but are not limited to, insulin mimicking, insulin sensitising, alpha and beta glucosidase enzyme inhibition, reduction of glucose uptake by small intestine, and increasing glucose intake by peripheral cells." (PMID 30805018, 2019). "Further studies are needed to determine the comparative effectiveness and safety of continuing insulin secretagogues and newer diabetes medications after insulin initiation." (PMID 30759121, 2019). "No changes from pre- to post-intervention were observed for percentage body fat, total cholesterol, insulin, HOMA-IR, and T2DM risk (Q-Diabetes)." (PMID 31870345, 2019). "The insulin independence rate in the CO group was 37.5% (three in eight subjects who were diabetes free pre-op, p = 0.23 vs. control, Fisher’s exact test) or 30% (three in 10 total CO subjects, p = 0.51 vs. control)." (PMID 31885286, 2019). "It is important to acknowledge that we did not assess overall quality of consistency with treatment guidelines for all people with T2D and CKD, as we only focused on dosing of non-insulin glucose lowering diabetes medications." (PMID 30777033, 2019). "Patients with insulin‐treated diabetes have more congestion and physicians should be vigilant for this and consider appropriate use of diuretics to try to achieve euvolaemia." (PMID 31271255, 2019). "It has been observed that blood glucose and HbA1c levels have significantly decreased in citral treated rats along with the significantly increased level of insulin as similar to glibenclamide treatment when compared to the diabetes control group." (PMID 30944708, 2019).